FAM85B (family with sequence similarity 85 member B)
Synonyms: lncRNA-HEIM
Gene: Long non-coding RNA gene on chromosome 8 (8,086,286 to 8,244,736, reverse strand). Ensembl gene ENSG00000253893.
Diseases named in the same sentence as FAM85B in open-access papers:
FAM85B is named in the same sentence as 3 diseases in open-access papers, as found by Europe PMC text mining. Sharing a sentence is not in itself a finding about the gene and the disease. The quoted sentences say what the papers report.
schizophrenia (2 papers, 2021 to 2022). A major psychotic disorder characterized by abnormalities in the perception or expression of reality. "The pseudogenes FAM86B3P and FAM85B were also identified from the SMR analysis, with FAM85B and the other non-coding gene cis-eQTLs for RP11-481A20.10 and RP11-481A20.11 in the same region having been indicated in mood instability and schizophrenia." (PMID 35079123, 2022).
FAM85B also shares sentences with these, for which no sentence is quoted: diabetes mellitus (1 paper); Obesity (1).